MET (MET proto-oncogene, receptor tyrosine kinase)
Diseases named in the same sentence as MET in open-access papers (continued):
Sharing a sentence is not in itself a finding about the gene and the disease.
metastatic melanoma (16 papers, 2008 to 2025). A melanoma that has spread from its primary site to another anatomic site. "For example, higher expression of MET might be associated with metastatic melanoma." (PMID 40954493, 2025). "When we performed this analysis, we found no significant quantitatively linear correlation between MACC1 and MET expression levels in nevi (R2 = 0.062), primary (R2 = 0.02), and metastatic melanomas (R2 = 0.14)." (PMID 37496665, 2023). "We previously demonstrated that the protein expression, as assessed by immunohistochemistry, of MET and PD-L1 strongly correlated in advanced, metastatic melanoma." (PMID 37444518, 2023). "We also found coexpression of relatively high levels of MACC1 and MET in the majority of metastatic melanoma cases." (PMID 37496665, 2023). "While MET expression median values were similar in primary and metastatic melanoma cell lines, we found a trend in higher values in the metastatic cell lines, which comprised the cell line with the highest expression value." (PMID 32659961, 2020). "Although a fraction of MBM exhibits immune cell subset enrichment and interferon response signatures and responds to ICi therapy, MET-expressing brain metastatic melanoma cells may benefit from HGF released by stromal cells to drive progression." (PMID 38386085, 2024). "Therefore, we evaluated if there is a correlation between MACC1 and MET expression in benign nevi, primary and metastatic melanomas." (PMID 37496665, 2023). "Our earlier paper described how c-MET could serve as a potential target against metastatic melanoma." (PMID 35954441, 2022). "MET expression by more than 20% of cells was present in 40% (17 of 42) of primary cutaneous melanoma, 45% (nine of 20) of primary mucosal melanoma, and 33% (seven of 21) of metastatic melanoma." (PMID 32659961, 2020). "As a result of our observation that EGFR and MET may regulate the invasion of primary and metastatic melanoma, we decided to put our attention to the invadopodia." (PMID 31638339, 2019). "Moreover, patient sample analysis confirmed the correlation of SR-BI with MITF and MET in metastatic melanoma lesions." (PMID 30823658, 2019). "Interestingly, higher levels of MET expression, although not statistically distinguishable between primary and metastatic melanomas, is associated with decreased patient survival in our study." (PMID 37496665, 2023). "On the other hand, seven (78%) of nine metastatic melanomas show intermediate to high expression of both MACC1 and MET." (PMID 37496665, 2023). "A phase II randomised discontinuation trial assessed cabozantinib (XL184), an orally bioavailable inhibitor of tyrosine kinases including VEGF receptors, MET, and AXL, in a cohort of patients with metastatic melanoma." (PMID 28103611, 2017). "However, this correlation appears stronger in metastatic melanomas, where seven (78%) of nine cases show intermediate to high expression of both MACC1 and MET." (PMID 37496665, 2023). "Overall, these data suggest that targeting the VEGFR, MET, and AXL pathways with cabozantinib may lead to improved outcomes in patients with metastatic melanoma." (PMID 28103611, 2017). "Moreover, a robust correlation between MET and PD-L1 expression was found in samples from metastatic melanoma and not in primary cutaneous or mucosal melanoma." (PMID 32659961, 2020). "One-hundred melanocytic lesions were evaluated for expression of MET and PD-L1 in a human tissue microarray (TMA) with benign nevi (17 patients), primary cutaneous melanomas (42 patients), primary mucosal melanomas (20 patients), and metastatic melanomas (21 patients)." (PMID 32659961, 2020).
adenoma (15 papers, 2000 to 2025). A neoplasm arising from the epithelium. "The genes CDH3, ECM1, IGFBP2, and MET, which are associated with cell adhesion, the extracellular matrix, and cancer cell invasion/metastasis, are also observed frequently increased in these two adenoma samples." (PMID 27100181, 2016). "MET overexpression was reported in 47.8% adenomas, 66.7% carcinomas and very high (86.4–93.8%) in distant metastasis." (PMID 34083590, 2021). "Intestinal organoid cultures with inducible MET deletion revealed MET signaling regulating intestinal homeostasis, regeneration and adenoma formation." (PMID 30211160, 2018). "Our group has shown that the receptor tyrosine kinase MET is overexpressed during all stages of the adenoma–carcinoma sequence." (PMID 15785735, 2005). "In CRC, MET is overexpressed in the vast majority of adenomas, invasive carcinomas, and metastases." (PMID 15785735, 2005). "In studies involving intestinal organoid cultures and mice with inducible MET deletion, HGF receptor signaling was found to play a crucial role in regulating intestinal homeostasis, regeneration, and adenoma formation." (PMID 39769452, 2024).
esophageal adenocarcinoma (15 papers, 2014 to 2025). A malignant tumor with glandular differentiation arising predominantly from Barrett mucosa in the lower third of the esophagus. "Specifically, MET gene amplification and consequent overexpression is an ‘oncogenic driver’ in a subset (∼5%) of gastric and esophageal adenocarcinomas, while MET mutations have been rarely reported in various hereditary and sporadic cancers including gastroesophageal adenocarcinomas (GEC)." (PMID 24983965, 2014). "The aim of this study was to investigate the ability of EMI-137, a mesenchymal–epithelial transition factor (c-MET)-targeting optical imaging tracer, to detect dysplasia in Barrett’s esophagus." (PMID 39513952, 2025). "Analysis of the GSE13898 dataset revealed a notable increase in MET mRNA expression in both Barrett’s esophagus (9.911 ± 0.160) and esophageal adenocarcinoma (9.398 ± 0.171) compared with NSE (8.080 ± 0.073; P < 0.0001)." (PMID 39513952, 2025). "Immunostaining of 89 esophageal adenocarcinoma samples showed that 58.06% overexpressed c-MET, whereas EGFR overexpression was noted in 27.42%." (PMID 39513952, 2025). "Taken together, these data indicate higher expression of MET mRNA and c-MET protein in Barrett’s esophagus and esophageal adenocarcinoma compared with NSE and benign conditions (inflammation and hyperplasia)." (PMID 39513952, 2025). "EMI-137 accumulates in dysplastic lesions within Barrett’s esophagus and also in c-MET–positive esophageal adenocarcinoma." (PMID 39513952, 2025). "EMI-137 accumulates in dysplastic lesions in Barrett’s esophagus and in c-MET–positive esophageal adenocarcinoma." (PMID 39513952, 2025). "Among all patients treated on trials with c-MET inhibitors in our series, the best result was stable disease for almost 10 months in a patient with esophageal adenocarcinoma who had received 3 prior therapies." (PMID 24742823, 2014). "Similarly, in the GSE26886 dataset, upregulation of MET mRNA expression was observed in both Barrett’s esophagus (−0.096 ± 0.198) and esophageal adenocarcinoma (0.447 ± 0.236) compared with NSE (−2.692 ± 0.235; P < 0.0001)." (PMID 39513952, 2025). "Efforts to increase diagnostic accuracy through FME have investigated several molecular markers such as EGFR, ErbB2 receptor tyrosine kinase 2, VEGF-A, fluorescent PARP1 inhibitor, chemokine receptor 4, heat shock protein 70, and c-MET for early esophageal adenocarcinoma detection." (PMID 39513952, 2025). "In a single-arm Phase II trial using the selective small molecule MET inhibitor AMG337, antitumor activity was observed in 18% of adults with MET-amplified gastric, gastroesophageal junction, and esophageal adenocarcinomas; however, significant adverse side effects were also observed." (PMID 40723207, 2025). "In this study, we therefore hypothesized that MET activation may lead to lapatinib resistance in HER2-driven esophageal adenocarcinoma, and tested the feasibility of MET targeting by small-molecule inhibitor Foretinib in EAC cells." (PMID 31772236, 2019). "Progress in targeted therapy in esophageal adenocarcinoma has been slow primarily due to failure of conventional markers in other gastrointestinal adenocarcinoma (KRAS, EGFR, PTEN, PIK3CA, and c-MET) to identify patients with esophageal adenocarcinoma who would respond to a targeted therapy." (PMID 28404924, 2017). "In a recent study, Liang and colleagues analyzed the mRNA expression level of MET and EGFR in esophageal adenocarcinoma by interrogating The Cancer Genome Atlas database, showing that MET mRNA is overexpressed in esophageal adenocarcinoma." (PMID 39513952, 2025). "MET mRNA expression analyses and c-MET immunostaining confirmed upregulation of c-MET in Barrett’s esophagus and esophageal adenocarcinoma compared with normal epithelium." (PMID 39513952, 2025).
esophageal adenocarcinoma (continued). "In a phase II trial, the experimental small molecule MET inhibitor AMG 337 was investigated in patients with gastric/gastroesophageal junction/esophageal adenocarcinoma, and a FISH assay with MET/CEP7 ≥ 2.0 as a cut-off was used." (PMID 35565287, 2022). "c-MET was selected as the molecular target in this study because marked c-MET immunostaining has been shown in Barrett’s esophagus dysplastic lesions and esophageal adenocarcinoma but absent or only modest immunostaining is observed in NDBE." (PMID 39513952, 2025).
metastasis (15 papers, 2013 to 2024). The spread or migration of cancer cells from one part of the body (where they first appeared) to another. "c-MET expression in CRC primary tumors has been found to be predictive of local tumor invasion and regional lymph node metastasis and higher c-MET levels have been found in synchronous CRC liver metastasis compared to levels obtained in matched primary tumors." (PMID 27793046, 2016). "Especially FGFR1 (13% in PTvs.N and 7% in Mvs.PT to 10% in AMP), FGFR3 (7% in PTvs.N and Mvs.PT to 2% in AMP), DDR2 in lymph node metastasis (13% in Mvs.PT to 3% in AMP) and MET (7% in PTvs.N and Mvs.PT to 2% AMP, FC 2.4) seem to be similarly overexpressed." (PMID 29743718, 2018). "Interestingly, our analysis revealed that the mRNA expressions levels of DPP4/CTNNB1/MET were more elevated in stage IV of THCA cancer, and were significantly elevated in metastasis tumor compared with the primary tumor." (PMID 35205190, 2022).
nasopharyngeal carcinoma (15 papers, 2013 to 2025). A carcinoma arising from the nasopharyngeal epithelium. "Amongst all developed c-MET inhibitors Pha665752, a potent ATP-competitive agent, was shown to exhibit the highest potential for radiosensitization in nasopharyngeal cancer cell lines." (PMID 33919702, 2021). "c-MET, nEGFR, H-Ras, and PI3K mutations were also related to cetuximab resistance in nasopharyngeal carcinoma." (PMID 29973197, 2018). "This study assessed the incidence and prognostic value of MET protein overexpression and gene amplification in locoregionally advanced nasopharyngeal carcinoma (NPC)." (PMID 25965822, 2015). "MET protein expression was evaluated in 376 patients with locoregionally advanced nasopharyngeal carcinoma." (PMID 25965822, 2015). "Targeting MET by tyrosine kinase inhibitor suppresses growth and invasion of nasopharyngeal carcinoma cell lines." (PMID 23573286, 2013). "Meanwhile, c-MET, nEGFR over-expression, H-Ras, and PI3K mutations could be as biomarker for cetuximab resistance in nasopharyngeal carcinoma." (PMID 29973197, 2018). "It has also been reported that c-MET inhibition may result in marked downregulation of TIGAR and intracellular production of NADPH in nasopharyngeal cancer." (PMID 32206103, 2020). "In conclusion, MET protein overexpression and gene amplification are independent prognostic factors for OS and DFS in locoregionally advanced nasopharyngeal carcinoma, and may provide therapeutic biomarkers to identify patients in whom MET inhibitors may be beneficial." (PMID 25965822, 2015).
endometrial cancer (14 papers, 2011 to 2025). Primary or metastatic malignant neoplasm involving the endometrium (mucous membrane that lines the endometrial cavity). "Since several c-MET inhibitors are FDA-approved drugs and in the late phases of the clinical trials, the next step is to launch a clinical trial targeting MET mutations in advanced endometrial cancers." (PMID 34439385, 2021). "First, the MET mutation was noted in 30% of advanced endometrial cancer cases and was associated with a poor clinical outcome; concurrent MET and KRAS mutations indicated the worst outcome." (PMID 34439385, 2021). "The selection of patients based on the germline MET genetic variant may prove more beneficial for patients with endometrial cancer receiving cisplatin-based therapy and could be a new therapeutic strategy in precision medicine." (PMID 34439385, 2021). "The co-occurrence of MET and PIK3CA or KRAS mutations might also mediate the resistance to c-MET inhibitors when targeting the MET mutation in endometrial cancer." (PMID 34439385, 2021). "In endometrial carcinomas, the expression of ER and MET correlated inversely and the coexpression of both receptors predicted response to hormonal therapy." (PMID 39742369, 2024). "Taken together, MET mutations highly influence the clinical outcome of advanced endometrial cancer, and KDR and KRAS mutations exhibit additional impacts on patients with a MET mutation." (PMID 34439385, 2021). "EGFR inhibitors, Her-2 inhibitors, MEK inhibitor and MET inhibitor in metastatic, advanced or recurrent endometrial cancer." (PMID 34944775, 2021). "Hepatocyte growth factor (HGF), also produced by stromal endometrial cells, supports the growth and proliferation of epithelial and stromal cells in the endometrium, and unregulated HGF/c-MET/Akt pathway activation is even shown to drive carcinogenesis in endometrial carcinoma." (PMID 40628401, 2025). "Second, our data showed MET is a potential therapeutic target for endometrial cancer." (PMID 34439385, 2021). "The MET/PIK3CA and MET/KRAS co-mutation may have biological impacts on endometrial cancer cells." (PMID 34439385, 2021). "In endometrial cancer, miR-152 inhibited tumor cell growth via targeting novel candidate targets E2F transcription factor 3 (E2F3), tyrosine kinase receptor (MET), and rapamycin-insensitive companion of mTOR (Rictor)." (PMID 34680020, 2021). "This notion was supported by our experiments in the endometrial cancer cell line, which showed that HGF induced delayed c-MET phosphorylation, accompanied by rapid dephosphorylation." (PMID 34439385, 2021). "Therefore, miR-200a-3p could regulate MET and indirectly act on the corresponding ZEB1 targets to promote the invasion and metastasis of endometrial cancer." (PMID 38916621, 2024).
liver fibrosis (14 papers, 2016 to 2026). "Notably, UbD deficiency (in UbD−/− mice) suppressed HGF/MET signaling and MDB formation, leading to reduced liver fibrosis." (PMID 42270593, 2026). "HGF/MET signaling is also necessary for reparative responses, activated upon liver injury, both during hepatocyte-mediated regeneration and liver regeneration associated with HPC expansion and exerts hepatoprotective effects against liver fibrosis through different mechanisms." (PMID 38138981, 2023).
metastatic colorectal cancer (14 papers, 2014 to 2024). "A phase II clinical trial (NCT03592641) is evaluating the efficacy and safety of savolitinib, a selective anti-MET tyrosine kinase inhibitor (TKI), in patients with MET-amplified metastatic colorectal cancer." (PMID 38790167, 2024). "In metastatic colorectal cancer, the inadvertent activation of evolutionarily methylation-silenced genes MET, RAB3IP and CHRM3 proto-oncogenes have been identified." (PMID 32905102, 2020). "In metastatic colorectal cancer, amplification and overexpression of MET is a key contributing factor to resistance to anti-EGFR therapies." (PMID 28388297, 2017). "Although the prevalence of MET amplification in untreated metastatic colorectal cancer was also reported to be low, we identified two of them in 10 patients." (PMID 24676216, 2014). "Moreover, MET gene amplification has been recognized as a mechanism of resistance to EGFR inhibitors in metastatic colorectal cancer and non-small-cell lung cancer (NSCLC)." (PMID 39598385, 2024). "Cabozantinib targets MET along with VEGFR2, making it effective in treating several metastatic cancers, including metastatic colorectal cancer." (PMID 39598385, 2024). "On the other hand, MET inhibition in patient‐derived xenografts of metastatic colorectal cancer with chromosome 7 low polysomy did not modify tumor growth." (PMID 28960893, 2017). "Prior studies reported a MET amplification rate of 9–18% in metastatic colorectal cancer (mCRC) but do not differentiate increased gene copy numbers due to chromosomal level aberrations from focal gene amplifications." (PMID 27421137, 2016).
pancreatic adenocarcinoma (14 papers, 2016 to 2023). "MET expression status from archival tumor samples was available for 6 patients, of whom 1 patient (700 mg cohort, pancreatic adenocarcinoma) was MET diagnostic positive, having 70 % of cells staining 2+ for MET expression." (PMID 27422720, 2016). "In addition, PAK1 is highly expressed in a proportion of pancreatic adenocarcinoma patients and its expression is significantly associated with MET positivity and linked to a widespread metastatic pattern." (PMID 30971268, 2019). "Finally, both the signalling pathways mediated ErbB1 and c-MET have been described for their associations with a more aggressive phenotype and poor prognosis in patients with pancreatic adenocarcinoma." (PMID 29285254, 2017). "Besides, MET also has a certain mutation probability in pancreatic adenocarcinoma." (PMID 36713541, 2022). "There have been many studies demonstrating MET as a poor prognostic gene for pancreatic adenocarcinoma, which is consistent with our findings." (PMID 37370756, 2023). "Crizotinib is a tyrosine kinase inhibitor that it can block peritoneal diffusion in pancreatic adenocarcinoma through inhibiting cancer cell proliferation and invasion, at least in part by the suppression of MET signal." (PMID 31412643, 2019). "Active human cancer-linked pancreatic stellate cells caused proliferation and microtube formation of microvascular endothelial cells by c-MET signal pathway, which exert a primary effect in human pancreatic adenocarcinoma progression." (PMID 31412643, 2019). "One report provided evidence that targeting MET in combination with gemcitabine may be effective in human pancreatic adenocarcinoma and ensured further clinical evaluation." (PMID 31412643, 2019). "MET expression was significantly increased in the acinar and ductal cells of CP patients with expression higher in pancreatic intraepithelial neoplasia (PanIN) 1A and 1B lesions, established precursors to invasive pancreatic adenocarcinoma." (PMID 27798657, 2016). "Hence, it can be speculated that MET is a candidate therapeutic target in pancreatic adenocarcinoma and highlighted a collaborative combination of drugs warranting clinical evaluation for pancreatic adenocarcinoma treatment." (PMID 31412643, 2019). "Compared with normal tissues, the expression levels of MET, DYNLL2, CDK1, TNFSF10, PIP5K1C, MSLN, and GKN1 were significantly increased in pancreatic adenocarcinoma cells (p < 0.05)." (PMID 37370756, 2023). "We identified seven prognostic genes (MET, DYNLL2, CDK1, TNFSF10, PIP5K1C, MSLN, GKN1) and validated that their related proteins, such as EGFR and MMP2, have a significant impact on the prognosis of pancreatic adenocarcinoma." (PMID 37370756, 2023).